POSTN (periostin)
Diseases named in the same sentence as POSTN in open-access papers (continued):
Sharing a sentence is not in itself a finding about the gene and the disease.
periodontal disease (14 papers, 2013 to 2025). "Our study being an observational study proves the association of GCF periostin levels with periodontal disease." (PMID 32274276, 2020). "Within the PDL, periostin has been shown to have a role in tissue remodeling in response to mechanical loading, and periostin-deficient mice develop an early onset periodontal disease phenotype." (PMID 31031642, 2019). "Salivary periostin levels are associated with the periodontal disease." (PMID 40177468, 2025). "Salivary periostin levels are associated with periodontal disease." (PMID 40177468, 2025). "The non-invasive approach validates the relevance of periostin as a biomarker and supports the growing trend toward using biomarkers for the early detection and management of periodontal diseases." (PMID 40177468, 2025). "The periostin level was higher in healthy individuals when compared to the individuals with periodontal diseases included in the study." (PMID 40177468, 2025). "Periostin has emerged as a promising biomarker in periodontal disease among the various molecular markers." (PMID 40177468, 2025). "Periostin is specifically present in the periodontal ligament, where it fulfills a variety of functions in tissue development and periodontal disease." (PMID 39859386, 2025). "With the course and severity of periodontal disease, the levels of periostin in gingival crevicular fluid declined correspondingly, and they were inversely linked with the clinical parameters." (PMID 38420070, 2024). "This meta-analysis was conducted to compare the gingival crevicular fluid (GCF) periostin levels in subjects having periodontal disease and healthy periodontium." (PMID 37173720, 2023). "The authors concluded that periostin increases due to the effort in tissue repair and regeneration during periodontal disease." (PMID 37173720, 2023). "The findings of the present study show that IL-39, IL-1β, and periostin levels were elevated in GCF in presence of periodontal disease." (PMID 35986791, 2022). "IL-39 levels were elevated in the presence of periodontal disease paralleling the increase in IL‐1β and periostin levels." (PMID 35986791, 2022). "The first to investigate the influence of spatial and temporal periodontal inflammation on the levels of the periostin in an inflammatory-induced periodontal disease model in vivo was Padial-Molina and colleagues in a series of animal and clinical studies." (PMID 34205668, 2021). "Periostin has been shown to be an essential protein in PDL integrity and its absence has been linked with periodontal disease." (PMID 32194440, 2020). "In our study GCF periostin levels were reduced with the increase in periodontal disease severity and these GCF periostin levels were inversely correlated with the clinical periodontal parameters." (PMID 32274276, 2020). "Given the emerging importance of molecular biomarkers in modern periodontal diagnostics, salivary periostin holds promise for enhancing the early detection, management, and monitoring of periodontal disease, ultimately improving patient outcomes and progressing toward patient-centered care." (PMID 40177468, 2025). "The AUC value, significantly higher than the null hypothesis value of 0.5, supports the strong predictive value of salivary periostin levels for periodontal disease." (PMID 40177468, 2025). "Therefore, exploring fresh perspectives about periostin salivary levels in different periodontal disorders is advisable." (PMID 40177468, 2025). "Considering the number of studies conducted in this field and the lack of a comprehensive conclusion, we aimed to conduct a comprehensive systematic review and meta-analysis regarding the possible role of GCF periostin as a new potential biomarker in the diagnosis of periodontal diseases." (PMID 37173720, 2023).
periodontal disease (continued). "When looking at the expression profile of periostin in GCF/wound fluid over time after periodontal surgery, it was shown that periostin levels increase after surgery, peak at 48 h and are higher in patients with the periodontal disease when compared to healthy controls." (PMID 34205668, 2021). "Within the limits of the study, it may be accepted that the GCF periostin level can be considered as a potential biomarker in periodontal disease activity evaluation." (PMID 32274276, 2020). "GCF periostin levels were gradually reduced with the increase in severity of periodontal disease." (PMID 32274276, 2020). "Since limited studies are available to find out the role of periostin in periodontal disease, our study was aimed to compare and evaluate the serum periostin and gingival crevicular fluid periostin levels in periodontally healthy, gingivitis and chronic periodontitis subjects." (PMID 32274276, 2020). "Studies have shown that inactivation of periostin leads to periodontal disease in mice." (PMID 25479552, 2014). "Also, taking into account that sampling from the GCF is a minimally invasive method, by sampling and measuring the concentration of periostin, we will obtain useful information for the early detection of periodontal disease in order to carry out timely and effective treatment." (PMID 37173720, 2023). "Considering the high prevalence of periodontal diseases worldwide and the destructive and irreversible effects of this disease on oral health and quality of life and the importance of early diagnosis, therefore, periostin can be used as a possible biomarker for the early diagnosis of this disease." (PMID 37173720, 2023). "Hence periostin may be used as a periodontal regeneration marker and the GCF periostin levels have been found to reduce with the increase of the severity of periodontal disease." (PMID 32274276, 2020). "The significant negative correlations with clinical measures of periodontal disease and the excellent diagnostic accuracy shown in the ROC analysis suggest that salivary periostin could be an important tool in the early detection and monitoring of periodontal disease." (PMID 40177468, 2025). "Periostin secreted from fibroblasts is found in various tissues such as serum, saliva and also GCF, and since the activity of periodontal disease can be diagnosed through GCF compounds, therefore, using the markers help to diagnose and prevent this disease." (PMID 37173720, 2023). "The aim of this study is to evaluate the gingival crevicular fluid (GCF) IL-39 levels in periodontal diseases and health and to correlate them to GCF levels of IL-1β and periostin." (PMID 35986791, 2022). "Decrease in GCF periostin levels was observed proportionally with periodontal disease progression and the degree of inflammation had affected the GCF periostin levels strongly and negatively." (PMID 32274276, 2020). "Therefore, this suggests that phosphorylation by FAM20C may regulate Periostin-mediated cell functions and it is of our particular future interest to investigate the biological role of phosphorylated Periostin and its molecular function in both healthy periodontal tissues and periodontal disease." (PMID 33051588, 2020). "The present study did not evaluate the relationship between periostin levels and the severity of periodontal disease, which is a limitation." (PMID 40177468, 2025). "Experimental mice without periostin proportionately suffered from severe periodontal disease and bone density reduction." (PMID 35659283, 2022).
Hypertension (13 papers, 2012 to 2025). The presence of chronic increased pressure in the systemic arterial system. "A large amount of evidence indicates that POSTN plays a vital role in coronary artery disease and cardiac fibrosis caused by hypertension." (PMID 40606601, 2025). "Inhibiting the expression of POSTN may be a promising method to attenuate the heart remodeling caused by hypertension." (PMID 40606601, 2025). "Experimental studies suggested a significant role of periostin in the development of arterial hypertension and hypertension-mediated organ damage." (PMID 34063373, 2021). "Further studies are needed to elucidate the role of periostin in the development of early stages of hypertensive diseases and vascular damage in these patients." (PMID 34063373, 2021). "Finally, periostin was found to be a promising marker of hypertension-induced cardiac remodeling and hypertensive nephropathy." (PMID 34063373, 2021). "Importantly, these associations held true when systolic blood pressure was added as a covariate, which suggests that periostin is correlated to renal injury independently of the degree of hypertension." (PMID 22403621, 2012). "Notably, while these findings establish POSTN as a biomarker of advanced fibrotic deterioration, current clinical evidence remains insufficient to validate its direct cardioprotective potential against hypertension-induced myocardial injury." (PMID 40606601, 2025). "In addition to periostin, literature retrieval and PCR verification were performed for other proteins that might be related to hypertension, such as Ahsg, Cst3, and Lrg1." (PMID 34084130, 2021). "However, nowadays arterial hypertension is considered a state of subclinical inflammation with numerous inflammatory markers elevated that may link PH with dysregulation of periostin level." (PMID 34063373, 2021). "Firstly, periostin was found to interact with RAAS; secondly, its expression in the arterial wall was elevated in a mice model of arterial hypertension." (PMID 34063373, 2021). "Patients diagnosed with hypertension had increased levels of periostin (p < 0.05) and TIMP-4 (p < 0.01) when compared to non-hypertensive patients." (PMID 34135421, 2021). "In multivariate analysis, neither the presence of hypertension nor blood pressure significantly influenced periostin level." (PMID 34063373, 2021). "Neither the presence of hypertension nor blood pressure and aPWV influenced periostin level." (PMID 34063373, 2021).
periodontitis (13 papers, 2020 to 2025). An acute or chronic inflammatory process that affects the tissues that surround and support the teeth. "Further studies need to be designed to evaluate the impact of systemic conditions/diseases on periostin levels that could confound the diagnosis of periodontitis and could benefit targeted screening of high-risk groups with systemic diseases and periodontitis." (PMID 40177468, 2025). "Periostin deficiency destroys the integrity of periodontal ligament, further leading to alveolar bone loss, periodontal tissue inflammation, periodontal pocket formation and other symptoms similar to periodontitis." (PMID 35562828, 2022). "Besides, inflammation may also alter periostin expression, as bacterial or inflammatory stimuli will cause a deficiency in PDL fibroblasts and subsequently reduce periostin production, thus decreasing periostin during periodontitis." (PMID 39221238, 2024). "The results of our investigation indicated that periostin expression in saliva was markedly decreased in patients with periodontitis." (PMID 40177468, 2025). "In the present study, we found a clear indirect correlation between the presence of periodontitis and alterations in salivary periostin levels, further solidifying periostin's potential as a reliable marker for periodontal tissue inflammation." (PMID 40177468, 2025). "Research on periostin levels in the gingival crevicular fluid (GCF) of patients with chronic periodontitis indicated reduced periostin levels in these individuals." (PMID 40177468, 2025). "The average salivary periostin levels were 4.63 in the healthy group and 1.24 in the periodontitis group (P < 0.05)." (PMID 40177468, 2025). "The present study aimed to investigate salivary periostin levels as a biomarker in individuals with periodontitis and healthy controls." (PMID 40177468, 2025). "The findings of our study also indicated that periostin levels in saliva are significantly lower in individuals with periodontitis." (PMID 40177468, 2025). "Salivary periostin holds significant promise for the early detection and management of periodontitis." (PMID 40177468, 2025). "Nevertheless, experimental animal studies provided most of the information regarding salivary periostin levels and periodontitis circumstances compared to human studies, prompting more human research for external validity." (PMID 40177468, 2025). "The results of this meta-analysis revealed that the mean concentration of GCF periostin in people with chronic periodontitis is lower than people with gingivitis and healthy people." (PMID 37173720, 2023). "In three studies, the mean of periostin level in GCF of chronic periodontitis and gingivitis patients were compared and included in this analysis." (PMID 37173720, 2023). "The results of their study indicated that the amount of periostin in the GCF decreases in the condition of periodontitis, which was consistent with our meta-analysis." (PMID 37173720, 2023). "Their results showed that the level of periostin was significantly lower in chronic and invasive periodontitis patients than in healthy individuals, which was consistent with the results of our meta-analysis." (PMID 37173720, 2023). "This review study examined the findings of studies related to the examination of periostin levels in people with chronic periodontitis and comparing it with healthy people and people with gingivitis." (PMID 37173720, 2023). "The syntheses of studies revealed a significant decrease in the periostin level of chronic periodontitis patients compared to the healthy individuals (SMD = -3.15, 95% CI = -4.45, -1.85, p < 0.001)." (PMID 37173720, 2023). "The results indicated that the total amount of periostin in the GCF of chronic periodontitis and gingivitis patients is significantly lower than that of healthy individuals." (PMID 37173720, 2023).
periodontitis (continued). "The syntheses of studies shown a significant decrease in the periostin level of chronic periodontitis patients compared to the gingivitis patients (SMD = -1.50, 95%CI = -2.52, -0.49, P = 0.003)." (PMID 37173720, 2023). "One of the strengths of this study is that this study, for the first time, compared the mean concentration of periostin in people with chronic periodontitis with healthy people and people with gingivitis." (PMID 37173720, 2023). "Results showed that GCF periostin level is significant lower in chronic periodontitis group compare to healthy people (the standardized mean difference (SMD) = -3.15, 95% CI = -4.45, -1.85, p < 0.001)." (PMID 37173720, 2023). "The present study findings showed that GCF IL-39, IL‐1β, and periostin total amounts were higher in patients with periodontitis and gingivitis than in the healthy controls." (PMID 35986791, 2022). "This is the first study to evaluate GCF IL-39, IL-1β, and periostin levels in periodontitis, gingivitis and periodontal health to the best of the authors’ knowledge." (PMID 35986791, 2022). "In contrast with the present study, GCF periostin levels were previously shown to decrease in relation to the severity of periodontitis." (PMID 35986791, 2022). "A study stated that periostin values increased in the presence of periodontitis in gingival crevicular fluid (GCF)." (PMID 35986791, 2022). "Periostin is highly expressed in the periodontal ligament, but the periostin level of gingival crevicular fluid in periodontitis patients was lower than in healthy people." (PMID 35562828, 2022). "Periostin level decreases, when the disease progressed, and the severity of the periodontitis was inversely proportional to periostin level." (PMID 32688410, 2020). "Periostin levels in GCF were comparatively low in the chronic periodontitis than in the gingivitis and healthy periodontium groups and the difference was statistically significant." (PMID 32274276, 2020). "This study was in accordance with the previous studies which reported that GCF periostin level in chronic periodontitis was lowest when compared to healthy periodontium." (PMID 32274276, 2020). "The present study was conducted to estimate and compare the gingival crevicular fluid and serum periostin levels in subjects having chronic periodontitis, gingivitis and healthy periodontium." (PMID 32274276, 2020). "In both conditions, GCF periostin level was significantly reduced, whereas saliva periostin level was elevated in aggressive periodontitis." (PMID 32688410, 2020). "GCF periostin levels were correlated inversely with the clinical parameters in chronic periodontitis patients." (PMID 32274276, 2020). "The purpose of the current study was to investigate GCF and serum periostin levels in individuals with clinically healthy periodontium, gingivitis and chronic periodontitis patients." (PMID 32274276, 2020). "Therefore, the clinical utility of salivary periostin as a potential screening tool for periodontitis warrants further investigation, particularly through large samples across diverse populations." (PMID 40177468, 2025). "Salivary periostin levels indirectly influence as a non-invasive biomarker of periodontitis." (PMID 40177468, 2025). "Hence, the present study aimed to assess salivary periostin levels as a non-invasive biomarker and to correlate with the clinical parameters among healthy and periodontitis patients." (PMID 40177468, 2025). "Also, the total amount of periostin in the GCF of people with chronic periodontitis is lower than that of people with gingivitis." (PMID 37173720, 2023). "Also, the periostin level of aggressive periodontitis was significantly lower than that of chronic periodontitis." (PMID 37173720, 2023). "Also, the level of periostin in the GCF of people with gingivitis was lower than the periodontitis group, but significantly higher than that of healthy people." (PMID 37173720, 2023).
periodontitis (continued). "However, in agreement with the present study, Arslan and co-workers found that periostin GCF levels decreased from the periodontitis group to the gingivitis and to the healthy control group." (PMID 35986791, 2022). "Decreased level of GCF periostin in periodontitis might be considered that this molecule has role in maintaining the function of normal periodontal tissue." (PMID 32274276, 2020). "Hence, a nexus between the two diseases may exist between osteopontin and variations in periostin levels in chronic periodontitis and ILDs." (PMID 38420070, 2024). "Local and low-grade infection associated with periodontitis might not have affected the serum periostin levels." (PMID 32274276, 2020). "There is growing evidence that periostin expression has a role in the healing process as well as other pathophysiological states of fibrosis which is present in both ILD and chronic periodontitis." (PMID 38420070, 2024). "Knockout of periostin, a key matrix protein of PDL, results in an early-onset periodontitis-like phenotype." (PMID 39171525, 2024). "In the comparison between chronic periodontitis group and healthy people, the results indicated that in people with chronic periodontitis, GCF periostin concentration is significantly lower than healthy people." (PMID 37173720, 2023). "In addition to periodontitis, other risk factors and diseases are also effective in changing the level of periostin in saliva, GCF, serum and urine, which could not be controlled in this study." (PMID 37173720, 2023). "Bacterial competition and the reduction in periodontal ligament fibroblasts numbers in periodontitis subjects, would have reduced GCF periostin levels." (PMID 32274276, 2020). "Clinical studies on aggressive periodontitis and chronic periodontitis revealed distinct salivary and GCF periostin profile." (PMID 32688410, 2020).